CD4 (CD4 molecule)
Diseases named in the same sentence as CD4 in open-access papers (continued):
Sharing a sentence is not in itself a finding about the gene and the disease.
COVID-19 (continued). "In summary, post-vaccination with the COVID-19 vaccine, patients may develop AA through an immune response mediated by CD4+Th2 and CD8+Tc2 cells, triggered by vaccine components or spike protein." (PMID 39021569, 2024). "Moreover, COVID-19 patients had increased expression of CD39 in CD4+ and CD8+ cells, NK cells, T regulatory cells, and monocytes." (PMID 38793691, 2024). "Notably, most PWH with COVID-19 in our study had CD4 + cell counts above 350 cells/mm3 and viral suppression, reinforcing that well-controlled HIV does not lead to higher mortality than that of the general population." (PMID 38789972, 2024). "Moreover, by ssGSEA, natural killer T cells, activated dendritic cells, activated CD4 T cells, neutrophils, and plasmacytoid dendritic cells were correlated with COVID-19 and PH, with SELE and CCL20 showing the strongest correlation with dendritic cells." (PMID 38653779, 2024). "In addition, CCL2 expression exhibited higher levels in classical monocytes and dendritic cells, while an upregulation of IL10 mRNA was detected in monocytes and CD4+ T cells of COVID-19 patients." (PMID 39625479, 2024). "In severe COVID-19 cases in humans, T-cell lymphopenia could be observed, characterized by profound CD4 and CD8 lymphocyte reduction." (PMID 39417078, 2024). "In terms of clinical significance, T. gondii infection can progress from the latent phase to the active phase through a decrease in CD8+ and CD4+ cells, which may lead to dangerous complications in COVID-19 patients." (PMID 38172676, 2024). "Increased CD4+ T cell senescence in severe/critical COVID-19 patients." (PMID 38377029, 2024). "Furthermore, an immune dysregulation has been shown in patients with long-term COVID-19 symptoms who had mild acute COVID-19 explained in T cell alterations, expressed by a decrease in the number of CD4+ and CD8+ effector memory cells." (PMID 39124710, 2024). "For example, the effect of hyperinflammation on oxygen saturation is exacerbated by hypercoagulability, a effect consistent with clinical experience in COVID-19 but attenuated by increasing the CD4+ and CD8+ T cell response and by the provision of effective antiviral therapy." (PMID 38820409, 2024). "COVID-19, as many other inflammation-driving diseases/syndromes, induces the excessive production of inflammatory cytokines (‘cytokine storm’) leading to activation of CD4- and CD8-positive lymphocytes." (PMID 38540218, 2024). "Notably, autoreactive CD4+ T cells were detected in ten out of ten non-COVID-19 patients with GBS, but in only two out of five post-COVID-19 patients with GBS." (PMID 38233524, 2024). "Answering these questions could provide a more comprehensive understanding of the CD4+ T-cell response to COVID-19 vaccination and potentially lead to the development of more effective vaccines." (PMID 38909235, 2024). "Moreover, COVID-19-naïve subjects showed a significantly increased frequency of AIM+ CD4 T cells after BA.2.86 stimulation compared with the negative control." (PMID 39772110, 2024). "Our early study that summarized the characteristics of 14 patients with HIV and SARS-CoV-2 co-infection found that a relatively high CD4 count among PLWH may more easily lead to COVID-19 death." (PMID 39127636, 2024). "Our findings highlighted special caution for patients with ASyS suffering from COVID-19, especially for those with a low CD4/CD8 ratio, and further mechanistic study may provide insights to better understand the immunopathogenesis of this unique scenario." (PMID 38500883, 2024). "From the perspective of cellular immune response, lymphopenia has been shown to be associated with disease severity and in convalescents from COVID-19 months after clinical recovery the CD4+ and CD8+ T cell compartments were found to be different compared to healthy controls." (PMID 38460013, 2024). "The role and mechanism of CD4 count in the development of COVID-19 need further investigations." (PMID 39127636, 2024).
COVID-19 (continued). "A low CD4+ T cell count may serve as a significant predictive indicator for identifying COVID-19 patients receiving azvudine treatment who are at an elevated risk of experiencing adverse outcomes." (PMID 39654887, 2024). "The peripheral blood mononuclear cells were isolated from enrolled study participants and flow cytometry analysis was done to assess the lymphocyte subsets of naive, effector, central memory, and effector memory CD4+ or CD8+ T cells in COVID-19 patients at 1 and 6-8 months after infection." (PMID 38860770, 2024). "Then, at the population level, we performed T-cell repertoire sequencing on 1,815 samples (from 1,521 COVID-19 subjects) as well as 3,500 controls to identify shared “public” T-cell receptors (TCRs) associated with SARS-CoV-2 infection from both CD8 and CD4 T cells." (PMID 39840037, 2024). "At this point, the vast majority of adults in the United States have been infected and/or received at least one dose of the COVID-19 vaccine; thus, going forward, characterizing pre-COVID-19 cross-reactive memory CD4+ and CD8+ T cells in unvaccinated COVID 19 patients will be very difficult." (PMID 38605956, 2024). "This suggests that K. pneumoniae has different immune function effects on CD4+ T cells than COVID-19, which may lead to B cell dysfunction." (PMID 38898888, 2024). "The immune response to COVID-19 vaccine is a T cell-dependent antibody response, where T cells are activated by antigen-presenting cells (APCs) and subsequently proliferate and differentiate into specific CD4+ T cells." (PMID 38181733, 2024). "Our data demonstrate that the percentage of CD4+ Tsens in peripheral blood may serve as a reliable biomarker for the prognosis of severe COVID-19 patients, especially in breakthrough infections." (PMID 38377029, 2024). "With respect to the effect size, however, CD39+CD45+ cells appeared to be a stronger predictor for COVID-19 severity as compared with TIM3+CD39+CD4+CD3+CD45+ lymphocytes, as indicated by an OR of 51.4 (95% CI 1.5 to 173) versus an OR of 22.6 (95% CI 1.8 to 277)." (PMID 38793691, 2024). "However, COVID-19 mRNA vaccines reportedly have a lower ability to induce CD8+ T cells than CD4+ T cells." (PMID 38409262, 2024). "The children with MISC_A had higher CD4+IL-2+/million CD3+ values (p-value: 0.03) compared to convalescent COVID-19, higher CD8+IL-2+/million CD3+ (p-value: 0.05) compared to healthy controls, and higher CD4−CD8−IL-2+/million CD3+ median (IQR) values compared to MISC_C (p-value: 0.03)." (PMID 39594853, 2024). "One study also showed that the CD4+ T cell response in COVID-19 convalescents after enhanced immunization with vaccines exhibited a resting state, and no epitope-specific S1 T-cell response could be detected." (PMID 38319108, 2024). "The CD4+ CM PD-1+ population was significantly higher in PLWH with COVID-19 at both time points." (PMID 39597537, 2024). "The frequencies of S-specific CD4+ memory T cells elicited by the two doses of mRNA COVID-19 vaccines and their distribution among the TCM, TEM, and TEMRA subsets are comparable with those induced by natural infection, and the patterns of contraction and estimated half-lives are also similar." (PMID 39460293, 2024). "Our data demonstrated that circulating CD4+ Tsen levels may serve as a reliable biomarker to predict COVID-19 severity and prognosis in elderly patients, especially in breakthrough infections." (PMID 38377029, 2024). "Furthermore, the median levels of CD4+ T cells on Day 36 were comparable to those of COVID-19 convalescent samples." (PMID 38675770, 2024). "In addition, the pre-COVID-19 CD4 count and CD4/CD8 ratio were similar between the two groups (p > 0.05)." (PMID 39772028, 2024). "It has been found that in critical COVID-19 patients a CD4+ T-cells depletion occurs, and it has been hypothesized that healthy CD4+ T-cells are attracted by infected CD4+ T-cells but are repelled by virions which can evade the immune machinery." (PMID 39524874, 2024).
COVID-19 (continued). "CD4+ EM1 PD-1+ was higher in the COVID-19 group compared to the control cohort (p < 0.001)." (PMID 39597537, 2024). "A third limitation is that we did not account for any HIV-related factors, such as CD4 count and viral suppression, which we have shown to be associated with COVID-19 outcomes." (PMID 39296577, 2024). "Considering the results for the COVID-19 group at 20–30 days after the onset of symptoms, PBMCs from this time point were chosen for in vitro cultivation with bLf to explore their effects on the subpopulations of NK, CD4+ T, and CD8+ T cells." (PMID 39483459, 2024). "Importantly, CD4+ T cells have been identified as an independent factor influencing disease progression in elderly COVID-19 patients." (PMID 39679195, 2024). "In contrast, the lowest frequencies of CCCs/SARS-CoV-2 cross-reactive IFN-γ-producing CD4+ T cells were detected in unvaccinated severely ill COVID-19 patients (severity scores 3 and 4) and in unvaccinated COVID-19 patients with fatal outcomes (severity score of 5)." (PMID 38605956, 2024). "Furthermore, plasma samples from severe COVID-19 patients demonstrated the capability to reduce the expression of CD73 on CD4+ and CD8+ T cells from a healthy donor." (PMID 39519310, 2024). "Interestingly, our study found that convalescent COVID-19 patients with elevated platelet counts had higher cell counts of total T cells, CD4 and CD8 T cells, and Tregs compared to convalescent patients with normal platelet counts." (PMID 39628664, 2024). "Indeed, severe COVID-19 is known to decrease the number and functionality of CD4 + T and CD8 + T-cells and induce a hyperinflammatory state that enhances fungal growth." (PMID 38605300, 2024). "Interestingly, a low CD4+ Th response was seen in subject 5, who had had COVID-19 before pregnancy, in addition to 3 vaccine doses." (PMID 38396707, 2024). "Importantly, in addition to controlling the levels of critical cytokines in COVID-19, our data shows that IFN-γ-licensed MSCs drastically reduced the apoptosis of CD4 and CD8 T-cells caused by the exposure of PBMCs to NS antigens." (PMID 39415027, 2024). "Multiple doses of the mRNA COVID-19 vaccines may result in much higher levels of IgG 4 antibodies, or also impaired activation of CD4 + and CD8 + T cells." (PMID 38280109, 2024). "CD4+ T cell responses during COVID-19 are correlated with disease severity, suggesting that a more severe acute SARS-CoV-2 infection could lead to a greater degree of T cell response dysregulation, potentially explaining chronic manifestations." (PMID 38482000, 2024). "When profiling the immune responses in the nasal mucosa and central nervous system, different studies identified an increase in early macrophages in the OE of TH (CD4+) cells and of cytotoxic T cells in the brain stem, parenchyma, and different brain regions in response to COVID-19." (PMID 38674011, 2024). "However, virus-specific CD4 + T cells were detected in COVID-19-recovered individuals and correlated with plasma levels of S-specific antibodies." (PMID 38806543, 2024). "Subsequently, we investigated whether CD4+ T-cell polyfunctionality differs in the nine pSOTR bivalent recipients depending on history of COVID-19." (PMID 38580714, 2024). "THX mouse mature antibody responses induced by NP16-CGG, Salmonella flagellin and Pfizer COVID-19 mRNA were presumably dependent on CD4+ T cells educated on huTECs or other human cells expressing MHC class II40–42, such as huB cells and huDCs, also present in THX mouse thymus." (PMID 38918608, 2024). "The observed correlations between RBC-TP ratio and CD4+ as well as CD8+ T cell frequencies suggest that altered immunological signatures may have an influence on capillary function in COVID-19." (PMID 38460013, 2024). "Furthermore, the therapeutic effects of NDV-RBD in A375 tumors engrafted in NCG mice receiving transfer of convalescent COVID-19 patient PBMCs were almost diminished upon CD8+ or CD4+ T cell depletion." (PMID 38609488, 2024).
COVID-19 (continued). "Studies have indicated that patients with severe COVID-19 exhibit elevated levels of pro-inflammatory cytokines (IL-6, tumor necrosis factor-α) and anti-inflammatory cytokines (IL-4, IL-10), along with decreased expression of CD4 and CD8 cells." (PMID 39040601, 2024). "An increased CD4+/CD8+ T-cell ratio has been reported in patients with severe COVID-19, suggesting that SARS-CoV-2 infection might preferentially impair CD8+ T cells, especially from the effector memory population." (PMID 39460293, 2024). "Younger age, prior COVID-19 before full vaccination, not having received additional vaccine doses and CD4 counts below 500 cells/mm3 were independently associated with BTI." (PMID 39062187, 2024). "Migrants who were ≥40 years of age, had a CD4 count of <200 cells/μL, had 2 or more comorbidities, and who were unvaccinated or incompletely vaccinated against SARS-CoV-2 were found to have a significantly increased risk of severe COVID-19." (PMID 38221982, 2024). "The dominance of HLA-positive CD4 lymphocytes in Group 1 aligns with prior studies, suggesting prolonged circulation in the bloodstream, indicative of a sustained activated cellular state post-COVID-19." (PMID 38468605, 2024). "Principal component analysis (PCA) applied to immune cell subsets revealed separation of patients with severe COVID-19 across the first principal component, with neutrophils, NK cells, and activated CD4+ and CD8+ T cells identified as the main drivers of immune cell variance." (PMID 38368384, 2024). "Aligning with the critical role for T cell immunity in long-term vaccine protection, our results suggest that COVID-19 vaccines may reduce serious breakthrough infections in seniors with lower CD4+ T cell senescence." (PMID 38377029, 2024). "Factors associated with a higher risk of severe COVID-19 included being aged ≥40 years, having a CD4 count <200 cells/μL, having 2 or more comorbidities, and nonreception or incomplete reception of the SARS-CoV-2 vaccines." (PMID 38221982, 2024). "The factors that predicted mortality amongst the hospitalized PLHIV were interruption of antiretroviral therapy, low CD4 + cell counts ≤ 200 cells/μL, unknown CD4 + cell count status, function impairment, co-infections, COVID-19 and liver disease." (PMID 38388345, 2024). "In fact, people with HIV (PWH) and normal CD4/CD8 ratio appear not to be more susceptible to severe forms of COVID-19 than the general population and they usually present a good seroconversion rate in response to vaccination against SARS-CoV-2." (PMID 38812512, 2024). "As the majority of PWH enrolled in COVID-19 vaccine trials have had normal CD4 T cell counts (>500 cells/mm3) and few comorbidities, these immunogenicity results may not be generalizable to the wide spectrum of PWH who are followed in Canadian centres." (PMID 38793698, 2024). "Monocytes from COVID-19 patients and post-trauma patients also have decreased CD4 expression, suggesting that the impaired immune response of SCD patients could be related to the immunological dysregulation observed in these disease states." (PMID 38899253, 2024). "The systemic inflammation induced by COVID-19, along with a significant influx of CD4+ T cells into cardiac tissues, may favor the development of AF." (PMID 39200954, 2024). "Collectively, these results indicate that CD4+ T cell senescence may serve as a prognostic biomarker for severe COVID-19 and diminished vaccine responses, especially among vulnerable elderly populations." (PMID 38377029, 2024). "Moreover, CD8+CD107a+ and CD4+T-bet+ appeared as relevant cell subsets to classify COVID-19 patients vs. HCs from D7 throughout D14–28." (PMID 39597661, 2024). "This case report analyzes the immune response to mRNA COVID-19 two-dose primary vaccination followed by three boosters in an IEI patient with marked CD4+ T-cell cytopenia and diminished thymic output, in comparison with that raised against latent, chronic cytomegalovirus (CMV) infection." (PMID 38675768, 2024).
COVID-19 (continued). "Next, we determined whether the highly conserved “universal” CD8+ and CD4+ T-cell epitopes were differentially recognized by T cells from asymptomatic (ASYMP) versus symptomatic (SYMP) COVID-19 patients." (PMID 38318166, 2024). "The independent correlation between fatigue severity and blood T cell phenotypes indicates a possible role of CD4+ T cells in the pathogenesis of post-COVID-19 fatigue, which might serve as a blood biomarker." (PMID 37924472, 2024). "Consistent with our findings, a recent study from Italy also showed a transient increase in CD4 count after COVID-19 vaccination, and the results remained after restricting the analysis to virosuppressed PWH with CD4 ≤200 cells/uL and more than six months of ART prior to vaccination." (PMID 39772028, 2024). "Interestingly, the concentration of D-dimer, a critical indicator of coagulation in COVID-19 patients, was positively correlated with neutrophil counts and negatively correlated with lymphocyte, total T, CD4+ T, and cytotoxic CD8+ T cell counts." (PMID 38674681, 2024). "COVID-19 vaccination with both BNT162b2 or ChAdOx1 induces robust CD4+ and CD8+ tetramer+ T cells toward immunodominant spike-specific epitopes in healthy participants and high-risk groups, including hematology patients, individuals with autoimmunity, and First Nations people." (PMID 39284068, 2024). "The three groups had similar CD4 counts and CD4/CD8 ratios before COVID-19 (all p > 0.05)." (PMID 39772028, 2024). "Thus, we focused on CD4+ T cell subsets from COVID-19 patients recruited during the first and second waves of the infection." (PMID 37809093, 2023). "Furthermore, COVID-19 recommendations in PLWH were limited to people with a CD4+ T cell count less than 200 cells/μL." (PMID 37515123, 2023). "Also, lymphopenia (the decrease of absolute CD4+ count and CD4/CD8 ratio) is a similar characteristic in COVID-19 and HIV patients that can be attributed to infection severity." (PMID 36789388, 2023). "However, when looking at the CD62L+ CD4+ T cell population, we found that recovered COVID-19 patients had greater frequencies of effector cells compared to non-severe patients (p<0.01), severe patients (p<0.01), and healthy controls (p<0.01)." (PMID 36817450, 2023). "Immune senescence, characterized by progressive lymphopenia with CD4 + T cell depletion and decreased regulatory T cell function in aging, could be a factor that makes older individuals more sensitive to severe COVID-19." (PMID 36631853, 2023). "Interestingly, the severely infected patients with COVID-19 were reported to have CD4+ T cells secreting lower levels of IFN-γ, IL-2, and TNF-α as compared to the patients with mild symptoms." (PMID 36679947, 2023). "In light of the ability of MSCs to suppress the differentiation of CD4 + T cells into Th1 and Th17 subpopulations, we examined whether the engineered MSCs still maintained such immunomodulatory effects in COVID-19." (PMID 37653459, 2023). "This suggests that the efficacy of inactivated vaccination against COVID-19 may be reduced in PLWH with depleted CD4+ T-cell counts." (PMID 37376408, 2023). "Research into immune irregularities in long-term COVID patients who initially experienced mild COVID-19 symptoms reveals T cell anomalies such as T cell exhaustion, diminished CD4+ and CD8+ effector memory cells, and increased PD1 expression on central memory cells lasting at least 13 months." (PMID 38131885, 2023). "Also, the observed increases in memory T cells (CD45RO) and CD4 T cells (CD3+ and RO+) were associated with lower CRP levels, potentially leading to COVID-19 recovery and immunity." (PMID 36986336, 2023). "Additionally, both CD4+ CD62L+ and CD8+ CD62L+ T cells were increased in severe COVID-19 patients with diabetes in our cohort, and CD4+ CD62L+ T cells were increased in severely ill COVID-19 patients with hypertension." (PMID 36817450, 2023).